ATP1B3 (ATPase Na+/K+ transporting subunit beta 3)
Diseases named in the same sentence as ATP1B3 in open-access papers (continued):
Sharing a sentence is not in itself a finding about the gene and the disease.
glioma (1 paper, 2025). A benign or malignant brain and spinal cord tumor that arises from glial cells (astrocytes, oligodendrocytes, ependymal cells). "The impact of ATP1B3 expression level on the overall survival rate of glioma patients was calculated using the R language package, and a survival curve was created." (PMID 40027130, 2025). "Concurrently, immunohistochemistry confirmation was performed on the glioma tissue sections that were collected, and the findings likewise verified that ATP1B3 expression increases with the malignant degree of the glioma." (PMID 40027130, 2025). "Following ATP1B3 knockdown, the ability of glioma cells to proliferate, migrate, and invade was identified using the Transwell assay and CCK-8." (PMID 40027130, 2025). "In this work, we investigated in detail how ATP1B3 promotes the migration, invasion, and proliferation of glioma cells." (PMID 40027130, 2025). "Analysis of the TCGA database revealed a correlation between the clinical features of glioma patients and ATP1B3 expression." (PMID 40027130, 2025). "In this study, we employed RNA interference technology to inhibit ATP1B3 expression in glioma cells." (PMID 40027130, 2025). "The Cancer Genome Atlas (TCGA), a public tumor database, and the Chinese Glioma Genome Atlas (CGGA) were used to evaluate the differential expression of ATP1B3 in glioma cells of various grades." (PMID 40027130, 2025). "Few studies have examined the impact of ATP1B3 in gliomas, despite numerous studies demonstrating its pro-cancer role in some malignancies." (PMID 40027130, 2025). "Its connection to patient survival and prognosis; The siRNA interference approach instantly reduced the amount of ATP1B3 expression in the glioma cell lines U87MG and U251MG." (PMID 40027130, 2025). "The results indicated that the expression level of ATP1B3 rose considerably with the grade of glioma (grade 2, grade 3, grade 4), with a P-value of less than 0.001." (PMID 40027130, 2025). "Database analysis revealed a negative correlation between the patients’ prognosis and the expression level of ATP1B3, and a positive correlation with the malignant degree of the glioma." (PMID 40027130, 2025). "As a result, this study’s online examination of gliomas of various degrees (grades 2, 3, and 4) in the CGGA database revealed that, with a statistical difference (P<0.05), the expression level of ATP1B3 also increased significantly as glioma grade increased." (PMID 40027130, 2025). "Glioma cell motility, invasion, and proliferation all decline when ATP1B3 expression is lowered." (PMID 40027130, 2025). "However, there is a dearth of domestic and international research on the mechanism of action of ATP1B3 and its role in gliomas." (PMID 40027130, 2025). "Glioma cells had significantly more ATP1B3 than the normal group (P<0.05)." (PMID 40027130, 2025). "The CGGA website was used to examine the expression level of ATP1B3 in gliomas of various grades." (PMID 40027130, 2025). "By controlling the MAPK and NF-κB signaling pathways, ATP1B3 may have a role in the invasion, migration, and proliferation of glioma cells." (PMID 40027130, 2025). "The glioma’s malignant growth was aided by the correlation coefficient of 0.67 with ATP1B3." (PMID 40027130, 2025). "Investigating ATP1B3 expression and mechanism in glioma cells was the goal of this work." (PMID 40027130, 2025). "ATP1B3 is expected to be a new potential glioma molecular marker." (PMID 40027130, 2025). "By influencing the MAPK/NF-κB and PPP1CA signaling pathways, ATP1B3 may control the malignant development of gliomas." (PMID 40027130, 2025). "Therefore, by altering the MAPK signaling pathway, ATP1B3 may have an impact on the malignant development of gliomas." (PMID 40027130, 2025). "Using immunofluorescence, the locations of ATP1B3 and PPP1CA in glioma cells were determined." (PMID 40027130, 2025).
leukoplakia (1 paper, 2023). A white patch or plaque on a mucous membrane that cannot be characterized clinically or pathologically as any other disease. "Some epithelial cells in leukoplakia showed CNVs as well as expression of various tumor-related genes similar to malignant cells, suggesting that CNV-driven expression of TP63 and ATP1B3 in leukoplakia plays a critical role in the progression to HNSCC." (PMID 38188682, 2023).
liver cirrhosis (1 paper, 2021). "The ATP1B3 protein level was elevated in tumor tissue compared to normal tissues, and its’ expression was associated with the high differentiated tumor and medical history of liver cirrhosis." (PMID 33868261, 2021).
rhabdomyosarcoma (1 paper, 2021). A rare aggressive malignant mesenchymal neoplasm arising from skeletal muscle. "Furthermore, the interaction between endogenous ATP1B3 and 3A was detected in EV-A71-infected human rhabdomyosarcoma cells, which suggests that 3A could interfere with the functions of ATP1B3 during infection." (PMID 33799649, 2021).
triple-negative breast carcinoma (1 paper, 2022). An invasive breast carcinoma which is negative for expression of estrogen receptor (ER), progesterone receptor (PR), and human epidermal growth factor receptor 2 (HER2). "In this study, freshly isolated triple-negative breast cancer biopsied cells obtained from consenting patients were subjected to flow cytometry and bioinformatic analysis to identify three endothelial cell subclusters: EC (ATP1B3), EC (HSPA1B), and EC (KRT7) in the tumor microenvironment." (PMID 35265720, 2022).
viral infections (1 paper, 2019). "Even if the biological relevance of increased ATP1B3 levels in BMDM upon serum deprivation is unknown, ATP1B3 has been shown to interfere with viral infections in human cells." (PMID 31331374, 2019).
tumor (24 papers, 2013 to 2026). "ATP1B3 expression was significantly associated with tumour invasion (T stage, P=0.015), lymph node metastasis (P=0.038) and cancer stage (AJCC, P=0.000)." (PMID 29137423, 2017). "In vitro validation revealed that ATP1B3 knockdown significantly inhibited tumor growth, indicating its potential anti-ATC activity." (PMID 42020364, 2026). "Treatment with siRNAs targeting TP63 (siTP63) or ATP1B3 (siATP1B3) significantly suppressed tumor-promoting functions of HNSCC cells, including cell viability, tumor sphere formation, migration, and invasion." (PMID 36828832, 2023). "As a control, we also included the analysis of ATP1B3 as its mRNA expression is unchanged between normal and tumor tissue." (PMID 36232400, 2022). "The protein level of ATP1B3 was elevated and the phosphorylation of ATP1B3 was downregulated in tumor tissue compared to paratumor tissues." (PMID 33868261, 2021). "We found that ATP1B3 was significantly correlated with tumor purity and B cell infiltration, CD8+ T infiltration, CD4+ T infiltration, Macrophage infiltration, Neutrophil infiltration, and Dendritic cell infiltration." (PMID 33868261, 2021). "The results revealed that ATP1B3 expression was positively correlated with the makers of CD8+ T, T cell, M1 Macrophage, B cell, TAM (tumor-associated macrophage), DCs, Th1 (T helper cell 1), Tfh (Follicular helper T cell), and T cell exhaustion." (PMID 33868261, 2021). "Further functional data is needed to elucidate the significance of ATP1B3 over-expression on tumor ECs and its relevance as a potential angiogenesis target." (PMID 24236063, 2013). "However, the exact role of ATP1B3 in tumor cell resistance to antineoplastic drugs requires further investigation." (PMID 40834150, 2025). "ATP1B3 protein may be related to gastric tumourigenesis and tumour progression by affecting the PI3K/AKT signalling pathway." (PMID 29137423, 2017). "As an effort toward evaluating the therapeutic potential of some of endothelial targets in humans that we identified, we focused on B7H3, Thy-1 and ATP1B3, which were among the more differentially expressed cell surface tumor-specific endothelial markers identified by MS in this study." (PMID 24236063, 2013). "Moreover, the univariate analysis proved that ATP1B3, tumor size, and differentiation were significantly associated with OS in HCC, and multivariate analysis showed that tumor size and differentiation were independent factors of OS in HCC using the CPTAC database." (PMID 33868261, 2021). "They employed FACS combined with the CD298 gene (ATP1B3) as a marker to discern and enumerate human-derived metastatic tumor cells in mouse peripheral tissues." (PMID 37627192, 2023).
cancer (13 papers, 2013 to 2025). A tumor composed of atypical neoplastic, often pleomorphic cells that invade other tissues. "As early as 2013, ATP1B3 and other angiogenesis targets identified by endothelial cells in human cancer tissues were discovered using proteomic analysis." (PMID 40027130, 2025). "Though there are currently few precise molecular mechanistic investigations on its involvement, it has been confirmed thus far that ATP1B3 plays a role in a number of malignancies and has the potential to become a new target for clinical therapy of cancer." (PMID 40027130, 2025). "The reaction rate of ATP-synthase decreased in both cancer cells, and the genes ATP1B3 and ATP6V1H were down-regulated." (PMID 37299011, 2023). "ATP1B3 expression was increased in various cancers, including PCa, and increased cell proliferation, migration, apoptosis, and epithelial-to-mesenchymal transition (EMT) of cells." (PMID 36497496, 2022). "Therefore, we examined the biological effects of ATP1B3 knockdown in cancer cells for the first time." (PMID 29137423, 2017). "IHC images indicated over-expression of ATP1B3 in carcinoma vessels compared to normal samples." (PMID 24236063, 2013). "The results showed that ADA, ATP1B3, DYNC1H1 and FTCD were differently expressed in non-cancer vs. cancer tissues of different stages, in cancer tissues of stage I vs. stage II or stage I vs. stage III." (PMID 35739471, 2022). "The remaining nine surface proteins identified solely (ANTXR1, AG1, DCBLD2, EFNB1, EMB, OSMR, SLC1A5) or found upregulated (ATP1B3 and ITGB1) on the MCF10A surface had no direct association with embryonic development signaling in the context of KRas mutant signaling in cancer cell lines." (PMID 27894102, 2016).
infection (3 papers, 2014 to 2022). The state of being infected such as from the introduction of a foreign agent such as serum, vaccine, antigenic substance or organism. "Interestingly, EC (ATP1B3) exhibited higher expression of phagocytosis-related genes in TNBC patients, RAB5A and EEA1, indicating these patients could be more susceptible to infection." (PMID 35265720, 2022). "In up-regulated genes of head kidney samples, 2 genes respond to infection by D. pseudospathaceum-clone I (HYAL2, PRF1), 3 to clone XII (RGCC, CYP27B1, CCR9) and 6 to the clone mix treatment (ITGA5, SIX1, ATP1B3, MEF2C, MLF1, MYLPF)." (PMID 25254967, 2014).
ATP1B3 also shares sentences with these, for which no sentence is quoted: colon cancer (3 papers); leukaemia (2); diffuse gastric cancer (1); Dupuytren’s Disease (1); fibrosarcoma (1); head and neck cancer (1); hepatocellular adenoma (1); intervertebral disc disease (1); lymphoma (1); male infertility (1); neuroblastoma (1); pancreatic cancer (1); polycystic kidney disease (1); Sepsis (1); type 2 diabetes mellitus (1).